CRCP (CGRP receptor component)
Description:
DNA-dependent RNA polymerase catalyzes the transcription of DNA into RNA using the four ribonucleoside triphosphates as substrates. Specific peripheric component of RNA polymerase III (Pol III) which synthesizes small non-coding RNAs including 5S rRNA, snRNAs, tRNAs and miRNAs from at least 500 distinct genomic loci. With POLR3H/RPC8 forms a mobile stalk that protrudes from Pol III core and functions primarily in transcription initiation (By similarity). Pol III plays a key role in sensing and limiting infection by intracellular bacteria and DNA viruses. Acts as nuclear and cytosolic DNA sensor involved in innate immune response. Can sense non-self dsDNA that serves as template for transcription into dsRNA. The non-self RNA polymerase III transcripts, such as Epstein-Barr virus-encoded RNAs (EBERs) induce type I interferon and NF-kappa-B through the RIG-I pathway. Accessory protein for the calcitonin gene-related peptide (CGRP) receptor. It modulates CGRP responsiveness in a variety of tissues.
Synonyms: CGRP-RCP; CGRPRCP; RCP; RCP9; C17; POLR3I; POLR3J; RPC9
Tractability: Small molecule: a structure with a bound ligand is known. Antibody: UniProt places it where antibodies can reach, with medium confidence; its Gene Ontology location is reachable by antibodies, with medium confidence; the Human Protein Atlas places it where antibodies can reach. PROTAC: ubiquitination databases record sites on it.
Gene: Protein-coding gene on chromosome 7 (66,114,604 to 66,154,568, forward strand). Ensembl gene ENSG00000241258.
Subcellular location: Nucleus; Cell membrane
Subcellular location (Human Protein Atlas): Nucleoplasm; Plasma membrane
Pathways (Reactome):
Gene expression (Transcription): RNA Polymerase III Abortive And Retractive Initiation; RNA Polymerase III Chain Elongation; RNA Polymerase III Transcription Initiation From Type 1 Promoter; RNA Polymerase III Transcription Initiation From Type 2 Promoter; RNA Polymerase III Transcription Initiation From Type 3 Promoter; RNA Polymerase III Transcription Termination
Immune System: Cytosolic sensors of pathogen-associated DNA
Gene Ontology:
Molecular function: DNA-directed RNA polymerase activity; protein binding; calcitonin gene-related peptide receptor activity; nucleotide binding
Biological process: termination of RNA polymerase III transcription; transcription by RNA polymerase III; transcription initiation at RNA polymerase III promoter; DNA-templated transcription initiation; G protein-coupled receptor signaling pathway
Cellular component: DNA polymerase III complex; nucleus; RNA polymerase III complex; cytosol; nucleoplasm; plasma membrane; acrosomal vesicle; RNA polymerase complex
Genetic constraint (gnomAD): Loss-of-function variants: 12 observed, 13.9 expected, observed/expected ratio (o/e) 0.86, 90% interval 0.55 to 1.4. The upper end of that interval is the gene's LOEUF score, 1.4, which puts it in group 5 of 6, group 1 being the genes least tolerant of losing a copy. Missense variants: 101 observed, 142.12 expected, observed/expected ratio (o/e) 0.71, 90% interval 0.6 to 0.84. Synonymous variants: 45 observed, 52.41 expected, observed/expected ratio (o/e) 0.86, 90% interval 0.68 to 1.1.
Homologues: Orthologues: chimpanzee CRCP (100% identical), chimpanzee CRCP (98% identical), rabbit CRCP (93% identical), mouse Crcp (89% identical), rat Crcp (86% identical), dog CRCP (82% identical), zebrafish crcp (71% identical), tropical clawed frog crcp (58% identical), Caenorhabditis elegans M106.7 (36% identical), Drosophila melanogaster Polr3I (28% identical).
Diseases named in the same sentence as CRCP in open-access papers:
CRCP is named in the same sentence as 6 diseases in open-access papers, as found by Europe PMC text mining. Sharing a sentence is not in itself a finding about the gene and the disease. The quoted sentences say what the papers report.
glioblastoma (1 paper, 2023). The most malignant astrocytic tumor (WHO grade IV). "Through multiple cox analysis, we identified CRCP as an independent risk factor in GBM and a potential novel target for treating glioblastoma." (PMID 37560473, 2023).
Hypertension (1 paper, 2010). The presence of chronic increased pressure in the systemic arterial system. "The calcitonin gene-related peptide is a vasodilator and its receptor CRCP has been previously implicated in hypertension in a small candidate gene association study of hypertension in Japanese individuals." (PMID 20838585, 2010).
neuroendocrine tumors (1 paper, 2023). "As CRCP encodes the protein which is a component of calcitonin gene-related peptide (CGRP) receptor and CGRP has been reported in neuroendocrine tumors, however, CRCP itself has not been mentioned by previous studies." (PMID 37560473, 2023).
primary biliary cirrhosis (1 paper, 2015). "The IKZF3 synonymous SNP rs907092 (MAF = 0.30) had been associated with primary biliary cirrhosis, and CRCP SNP rs875971 (MAF = 0.47, located in 3′ UTR) with aortic root diameter alternations." (PMID 26331722, 2015).
cancer (1 paper, 2020). A tumor composed of atypical neoplastic, often pleomorphic cells that invade other tissues. "Awareness of the CRCP and its use in cbLB is increasing and may represent the next generation of cancer cbLB that becomes in particular beneficial in combination with whole genome sequencing applications." (PMID 32218149, 2020).
CRCP also shares sentences with these, for which no sentence is quoted: migraine (1 paper).